CLNS1A (chloride nucleotide-sensitive channel 1A)
Description:
Involved in both the assembly of spliceosomal snRNPs and the methylation of Sm proteins. Chaperone that regulates the assembly of spliceosomal U1, U2, U4 and U5 small nuclear ribonucleoproteins (snRNPs), the building blocks of the spliceosome, and thereby plays an important role in the splicing of cellular pre-mRNAs. Most spliceosomal snRNPs contain a common set of Sm proteins SNRPB, SNRPD1, SNRPD2, SNRPD3, SNRPE, SNRPF and SNRPG that assemble in a heptameric protein ring on the Sm site of the small nuclear RNA to form the core snRNP (Sm core). In the cytosol, the Sm proteins SNRPD1, SNRPD2, SNRPE, SNRPF and SNRPG are trapped in an inactive 6S pICln-Sm complex by the chaperone CLNS1A that controls the assembly of the core snRNP. Dissociation by the SMN complex of CLNS1A from the trapped Sm proteins and their transfer to an SMN-Sm complex triggers the assembly of core snRNPs and their transport to the nucleus.
Synonyms: ClCI; ICLN; CLNS1B
Tractability: Small molecule: a structure with a bound ligand is known. Antibody: its Gene Ontology location is reachable by antibodies, with high confidence. PROTAC: ubiquitination databases record sites on it; its protein half-life has been measured.
Gene: Protein-coding gene on chromosome 11 (77,514,936 to 77,637,809, reverse strand). Ensembl gene ENSG00000074201.
Subcellular location: Cytoplasm, cytosol; Nucleus; Cytoplasm, cytoskeleton
Subcellular location (Human Protein Atlas): Cytosol; Nucleoplasm; Connecting piece; Microtubules; Mid piece; Primary cilium; Principal piece
Pathways (Reactome):
Metabolism of RNA: snRNP Assembly
Gene Ontology:
Molecular function: protein binding; RNA binding
Biological process: spliceosomal snRNP assembly; mRNA cis splicing, via spliceosome; positive regulation of mRNA splicing, via spliceosome; cell volume homeostasis; chloride transport
Cellular component: cytosol; methylosome; microtubule cytoskeleton; nucleoplasm; nucleus; pICln-Sm protein complex; plasma membrane; spliceosomal complex; cytoskeleton
Genetic constraint (gnomAD): Loss-of-function variants: 9 observed, 20.23 expected, observed/expected ratio (o/e) 0.44, 90% interval 0.27 to 0.78. The upper end of that interval is the gene's LOEUF score, 0.78, which puts it in group 3 of 6, group 1 being the genes least tolerant of losing a copy. Missense variants: 171 observed, 213.19 expected, observed/expected ratio (o/e) 0.8, 90% interval 0.71 to 0.91. Synonymous variants: 71 observed, 78.5 expected, observed/expected ratio (o/e) 0.9, 90% interval 0.75 to 1.1.
Homologues: Orthologues: chimpanzee CLNS1A (100% identical), macaque CLNS1A (100% identical), dog CLNS1A (93% identical), rabbit CLNS1A (93% identical), mouse Clns1a (91% identical), guinea pig CLNS1A (90% identical), rat Clns1a (90% identical), pig CLNS1A (85% identical), tropical clawed frog clns1a (72% identical), zebrafish clns1a (69% identical), Caenorhabditis elegans icln-1 (31% identical), Drosophila melanogaster icln (27% identical).
Diseases named in the same sentence as CLNS1A in open-access papers:
CLNS1A is named in the same sentence as 9 diseases in open-access papers, as found by Europe PMC text mining. Sharing a sentence is not in itself a finding about the gene and the disease. The quoted sentences say what the papers report.
breast carcinoma (3 papers, 2021 to 2024). "While not implicated in this study regarding hepatocellular cancer, the CLNS1A gene has been implicated in other cancers, especially breast cancer." (PMID 38132437, 2023). "Amplification of CLNS1A was linked to worse outcomes in luminal breast-cancer tumors, possibly by helping to recruit proteins to the PRMT5 complex." (PMID 38132437, 2023). "CLNS1A has also been described in malignant gliomas, but data for breast cancer is very limited." (PMID 34439272, 2021). "Additionally, CLNS1A amplification has been observed in malignant gliomas and breast cancer." (PMID 39857609, 2024). "We map the presence of splicing-related genes in breast cancer, describing three novel genes, LSM1, CLNS1A, and ILF2, that have an oncogenic role and can be modulated with BET inhibitors." (PMID 34439272, 2021). "Moreover, when the presence of CNAs in our selected genes was analyzed in different tumor types (GDC Data Portal; 67 primary sites), breast cancer was one of most frequently amplified for LSM1, CLNS1A, and ILF2." (PMID 34439272, 2021).
malignant glioma (3 papers, 2020 to 2024). A grade III or grade IV glioma arising from the central nervous system. "CLNS1A knockdown increased sensitivity to PRMT5 inhibitor EPZ015666 in malignant glioma, which may due to the reducing of splicing capacity." (PMID 32373523, 2020).
prostate carcinoma (3 papers, 2021 to 2024). A carcinoma that arises from epithelial cells of the prostate gland. "Gene set enrichment analysis revealed an association between DENND2D expression and the negative regulation of MYC target genes, including MAD2L1, ERH, and CLNS1A, which are overexpressed in prostate cancer and associated with poor survival." (PMID 39857609, 2024). "Interestingly, the PRMT5 cofactor chloride nucleotide-sensitive channel 1A (pICLn) is reported to play a role in PRMT5-H4R3me2–mediated gene regulation in prostate cancer." (PMID 37861290, 2023). "Notably, CLNS1A cooperates with the protein arginine methyltransferase 5, which functions as an epigenetic activator of androgen receptor transcription in castration-resistant prostate cancer." (PMID 39857609, 2024). "CLNS1A cooperates with the protein PRMT5 and functions as an epigenetic activator of AR transcription in castration resistance prostate cancer." (PMID 34439272, 2021).
endothelial dysfunction (1 paper, 2025). In vascular diseases, endothelial dysfunction is a systemic pathological state of the endothelium (the inner lining of blood vessels) and can be broadly defined as an imbalance between vasodilating and vasoconstricting substances produced by (or acting on) the endothelium. "These included genes such as CLNS1A, UGP2, RNF216, PHGDH, CKAP4, and IL6R, many of which are known to participate in inflammatory pathways, oxidative stress, and endothelial dysfunction." (PMID 41262879, 2025).
CLNS1A also shares sentences with these, for which no sentence is quoted: cancer (3 papers); co‐infection (1); glioma (1); hepatocellular carcinoma (1); tumor (1).